NR0B1 (nuclear receptor subfamily 0 group B member 1)
Description:
Nuclear receptor that lacks a DNA-binding domain and acts as a corepressor that inhibits the transcriptional activity of other nuclear receptors through heterodimeric interactions. Component of a cascade required for the development of the hypothalamic-pituitary-adrenal-gonadal axis. May also have a role in the development of the embryo and in the maintenance of embryonic stem cell pluripotency (By similarity).
Synonyms: AHC; DAX1; AHCH; AHX; DAX-1; DSS; GTD; HHG; NROB1; SRXY2
Tractability: Small molecule: a structure with a bound ligand is known; it belongs to a druggable protein family. PROTAC: a small molecule that binds it is known.
Target class: Transcription factor; Nuclear hormone receptor subfamily 0 group B; Nuclear hormone receptor subfamily 0 group B member 1; Nuclear receptor; Nuclear hormone receptor subfamily 0
Gene: Protein-coding gene on chromosome X (30,304,206 to 30,309,390, reverse strand). Ensembl gene ENSG00000169297.
Subcellular location: Nucleus; Cytoplasm
Subcellular location (Human Protein Atlas): Nuclear speckles; Centriolar satellite; Vesicles
Pathways (Reactome):
Gene expression (Transcription): Nuclear Receptor transcription pathway
Gene Ontology:
Molecular function: DNA hairpin binding; nuclear receptor binding; protein binding; protein domain specific binding; protein homodimerization activity; RNA binding; RNA polymerase II-specific DNA-binding transcription factor binding; transcription corepressor activity; nucleic acid binding
Biological process: adrenal gland development; gonad development; intracellular protein localization; male gonad development; negative regulation of DNA-templated transcription; negative regulation of gluconeogenesis; negative regulation of intracellular steroid hormone receptor signaling pathway; negative regulation of steroid biosynthetic process; negative regulation of transcription by RNA polymerase II; hypothalamus development; pituitary gland development; sex determination; spermatogenesis; developmental process involved in reproduction
Cellular component: centriolar satellite; cytoplasm; membrane; nuclear speck; nucleus; ribosome; chromatin; nucleoplasm
Homologues: Orthologues: chimpanzee NR0B1 (99% identical), macaque NR0B1 (97% identical), rabbit NR0B1 (79% identical), pig NR0B1 (78% identical), rat Nr0b1 (66% identical), mouse Nr0b1 (66% identical), guinea pig NR0B1 (57% identical), tropical clawed frog nr0b1 (32% identical), zebrafish nr0b1 (30% identical). Paralogues in human: NR0B2 (20% identical).
Diseases named in the same sentence as NR0B1 in open-access papers:
NR0B1 is named in the same sentence as 158 diseases in open-access papers, as found by Europe PMC text mining. Sharing a sentence is not in itself a finding about the gene and the disease. The quoted sentences say what the papers report.
adrenal hypoplasia (45 papers, 2007 to 2025). "Deletions or mutations of DAX-1 (dosage-sensitive sex reversal, adrenal hypoplasia critical region on chromosome X, gene 1), also known as NR0B1 (nuclear receptor subfamily 0, group B, member 1), cause the X-linked form of AHC." (PMID 41300587, 2025). "While NR0B1 has long been shown to play a role in adrenal development, and its loss of function is associated with adrenal hypoplasia, recent research on hepatocytes has suggested that NR0B1 KO leads to inflammatory injury." (PMID 37953774, 2023). "Specific variants of the NR0B1 gene (the coding gene for the DAX-1 [dosage sensitive sex-reversal, adrenal hypoplasia locus on the X-chromosome, gene 1] protein), including point variants and delete variants, have been shown to cause X-linked CAH10,11." (PMID 34373561, 2021). "Pathogenic variants in NR0B1 (or Dosage-sensitive sex reversal, adrenal hypoplasia critical region, on chromosome X gene, DAX1; chr Xp21.2) are usually causative of X-linked adrenal hypoplasia congenita." (PMID 34502334, 2021). "Here, we describe a novel pathogenic frameshift variant in NR0B1 associated with congenital adrenal hypoplasia by whole exome sequencing in an Iranian case for the first time." (PMID 34938333, 2021). "Here, we describe a novel pathogenic frameshift variant in NR0B1 associated with congenital adrenal hypoplasia by whole exome sequencing in an Iranian case with high level of testosterone." (PMID 34938333, 2021). "First, genetic forms of congenital adrenal hypoplasia, such as NR0B1 variants and IMAGe syndrome are known to show variable presentation of AI in terms of onset age and disease severity." (PMID 30403727, 2018). "The deletion of NR0B1 causes congenital adrenal hypoplasia, whereas its duplication leads to a pseudo-female phenotype and gonadal dysgenesis." (PMID 26840413, 2016). "Finally, after cortisol deficiency was detected, expanded genetic testing revealed a mutation in the NR0B1 gene, which led to a diagnosis of congenital adrenal hypoplasia." (PMID 38075942, 2023). "In addition, a gene variation that causes congenital adrenal hypoplasia, NR0B1 (encoding DAX1), is adjacent to the DMD gene on the X chromosome, providing a potential mechanistic link between DMD and adrenal insufficiency." (PMID 36036925, 2022). "NR0B1 is considered to be an anti-testis gene responsible for gonadal dysgenesis, and loss-of-function mutations in this gene are accountable for congenital adrenal hypoplasia and hypogonadotropic hypogonadism." (PMID 26980296, 2016). "NR0B1 may be a common cause of congenital adrenal hypoplasia in our population." (PMID 34938333, 2021). "Alterations in the dosage of NR0B1 lead to adrenal hypoplasia or to 46XY sex reversal, which is observed in the patient included in this study." (PMID 39062680, 2024). "The second group is adrenal hypoplasia, including X-linked adrenal hypoplasia congenita (AHC) caused by NR0B1, adrenal hypoplasia caused by steroidogenic factor-1/NR5A1, IMAGe syndrome caused by CDKN1C and MIRAGE syndrome caused by SAMD9." (PMID 34193132, 2021). "Hence, a multigene next-generation sequencing (NGS) panel for genes associated with congenital adrenal hypoplasia (CDKN1C, NNT, NR0B1, POLE, POMC, POR, SAMD9 e TBX19) was conducted and the pathogenic variant in the NR0B1 gene c.1273A>G p.(Arg425Gly) was found." (PMID 40013223, 2025). "Genetic testing for the NR0B1 (DAX1), which was involved in X‐linked congenital adrenal hypoplasia (MIM# 300200), was negative." (PMID 29178636, 2017). "Furthermore, a small inversion immediately upstream of NR0B1 has been identified in a patient with congenital adrenal hypoplasia." (PMID 22518125, 2012). "Moreover, within the 2 mb window, different H3K27ac marks could be correlated to the same gene, potentially allowing previously unknown enhancers to be grouped, for instance in the adrenal around the adrenal hypoplasia gene, NR0B1, located on the X chromosome." (PMID 32764605, 2020).
adrenal hypoplasia (continued). "No mutation was found in the NR0B1 and MC2R genes excluding congenital adrenal hypoplasia and FGD type 1." (PMID 21274326, 2010). "Children (n = 22) who had been diagnosed with salt-losing forms of adrenal hypoplasia (19 isolated cases, 3 familial), and who were negative for mutations in DAX1 (NR0B1) and SF1 (NR5A1)." (PMID 17223989, 2007).
adrenal hypoplasia congenita (43 papers, 2005 to 2025). "Genetic testing revealed a deletion in the CSNK2A1 gene, linked to Okur-Chung syndrome, along with a pathogenic NR0B1 variant, confirming adrenal hypoplasia congenita and hypogonadotropic hypogonadism." (PMID 40013223, 2025). "NR0B1 regulates the early stage of testicular differentiation, and its mutation most often causes adrenal hypoplasia congenita and gonadal dysplasia." (PMID 34276780, 2021). "Among these, NR0B1-related adrenal hypoplasia congenita (AHC) represents a distinctive X-linked disorder characterized by combined adrenal insufficiency and hypogonadotropic hypogonadism (HH) due to loss-of-function variants in the NR0B1 gene encoding the DAX-1 protein." (PMID 41523372, 2025). "Consistent with its function, duplication of the X region containing NR0B1 is associated with male-to-female sex reversal in XY individuals, and loss-of-function mutations in NR0B1 are responsible for X-linked adrenal hypoplasia congenita, a disorder characterized by hypogonadotropic hypogonadism." (PMID 38764035, 2024). "X‐linked adrenal hypoplasia congenita is produced by variants of NR0B1." (PMID 37118935, 2023). "Defects in this process may cause the cytomegalic form of adrenal hypoplasia congenita, a syndrome of adrenal insufficiency due to altered postnatal adrenocortical differentiation due to mutations in the NR0B1 (DAX-1) gene [reviewed in Ref." (PMID 25741319, 2015). "Mutations in DAX1 [dosage-sensitive sex reversal-adrenal hypoplasia congenita (AHC) critical region on the X chromosome gene 1; NR0B1] cause X-linked AHC, a disease characterized by primary adrenal failure in infancy or childhood and reproductive abnormalities later in life." (PMID 15847682, 2005). "Variants of NR0B1 (OMIM* 300437) give rise to both adrenal hypoplasia congenita (AHC) and hypogonadotropic hypogonadism (HH)." (PMID 37118935, 2023). "One boy with a NR0B1 mutation and X-linked adrenal hypoplasia congenita (AHC) had macrophallia and another one had cryptorchidism." (PMID 26523528, 2016). "Boys carrying mutations in the NR0B1 gene develop adrenal failure (adrenal hypoplasia congenital, AHC) and showed impaired sexual development at puberty, followed by infertility." (PMID 22761912, 2012). "Boys carrying mutations in the NR0B1 gene develop adrenal hypoplasia congenita (AHC) and impaired sexual development due to the combination of hypogonadotropic hypogonadism (HH) and primary defects in spermatogenesis." (PMID 22761912, 2012). "Among these, NR0B1-related adrenal hypoplasia congenita (AHC) is a distinctive X-linked disorder that may present beyond infancy and occasionally mimic congenital adrenal hyperplasia (CAH)." (PMID 41523372, 2025). "DAX-1 (Dosage-sensitive sex reversal-Adrenal hypoplasia congenita critical region on the X chromosome 1, genetically named as NR0B1) plays a main role in human development of adrenal glands and reproductive organ." (PMID 38279818, 2024). "NR0B1 (HGNC ID, HGNC:7960; chromosomal location, Xp21.2) encodes a protein (NP_000466), also known as the dosage-sensitive sex reversal-adrenal hypoplasia congenita critical region on the X chromosome protein 1 (DAX1)." (PMID 37189438, 2023). "Dosage-sensitive sex reversal-adrenal hypoplasia congenita critical region on the X chromosome, gene 1 (DAX1; NR0B1) represses the transcription of various genes." (PMID 36430486, 2022). "The dosage-sensitive sex reversal adrenal hypoplasia congenita critical region on the X chromosome, gene 1 (DAX-1, NR0B1), is an orphan nuclear receptor (NR), which lacks a known endogenous receptor ligand." (PMID 36233086, 2022). "X-linked congenital adrenal hypoplasia (adrenal hypoplasia congenita, AHC) primarily affects boys and is associated with disruption of the nuclear receptor, DAX-1 (encoded by NR0B1)." (PMID 33381483, 2020). "NR0B1 is a transcription factor gene isolated from the dosage-sensitive sex reversal adrenal hypoplasia congenita critical region on Xp21." (PMID 26542297, 2015).
adrenal hypoplasia congenita (continued). "Interestingly, this region includes the NR0B1 (nuclear receptor subfamily 0, group B, member 1) gene, also known as DAX1 (dosage-sensitive sex reversal-adrenal hypoplasia congenita critical region on the X chromosome, gene 1)." (PMID 39062680, 2024). "The dosage-sensitive sex reversal-adrenal hypoplasia congenita critical region on the X chromosome, gene 1 (DAX1; NR0B1), is classified as an orphan nuclear receptor without specific ligands that functions as a negative transcriptional regulator of various target genes." (PMID 36430486, 2022). "In addition, two genes responsible for the X-linked forms of Kallmann syndrome and CHH associated with adrenal hypoplasia congenita (KAL1 and NR0B1, respectively) were also screened as previously reported." (PMID 22679506, 2012). "DAX1 encoded by NR0B1, when mutated, is responsible for X-linked adrenal hypoplasia congenita (AHC)." (PMID 15847682, 2005). "X‐linked adrenal hypoplasia congenita (AHC) is a rare disorder, often manifesting as primary adrenal insufficiency (PAI) and hypogonadotropic hypogonadism (HH), and caused by variants of NR0B1, most of which are frame‐shifting variants, and few splice‐site variants." (PMID 37118935, 2023). "The dosage-sensitive sex reversal adrenal hypoplasia congenita critical region on the X chromosome, gene 1 (DAX-1, NR0B1), is an orphan nuclear receptor that acts as a transcriptional co-repressor of various genes." (PMID 36233086, 2022). "The dosage-sensitive sex reversal-adrenal hypoplasia congenita critical region on the X chromosome, gene 1 (DAX1), also known as Nr0b1, is an orphan nuclear receptor." (PMID 30208164, 2018).
hypogonadotropic hypogonadism (33 papers, 2008 to 2025). Abnormal ovarian or testicular function due to insufficient hormonal stimulation from the hypothalamic-pituitary axis. "Overall, the hypogonadotropic hypogonadism associated with NR0B1 variants appears to be relatively mild and micropenis at birth is rare in individuals with NR0B1 variants." (PMID 37189438, 2023). "Congenital adrenal hypoplasia and hypogonadotropic hypogonadism are the most well-known phenotypes caused by NR0B1 variants." (PMID 37189438, 2023). "NR0B1 pathogenic variants can cause congenital adrenal hypoplasia or primary adrenal insufficiency in early childhood usually associated with hypogonadotropic hypogonadism." (PMID 35432221, 2022). "All boys with AHC with DAX-1(NR0B1) gene mutation develop delayed puberty due to hypogonadotropic hypogonadism and needs close follow-up during pubertal age." (PMID 35495001, 2022). "NR0B1 mutations usually result in primary adrenal insufficiency and hypogonadotropic hypogonadism; however, there are some reports of patients with elevated levels of testosterone." (PMID 34938333, 2021). "X-linked congenital adrenal hypoplasia due to NR0B1 mutation is characterized by hypogonadotropic hypogonadism (HH) and infertility." (PMID 34938333, 2021). "Hypogonadotropic hypogonadism (HH) is the most frequently observed puberty disorder that is caused by mutations in the NR0B1 (DAX1) gene and is due to impaired gonadotropin synthesis and release." (PMID 27656210, 2016). "For example, boys with X-linked adrenal hypoplasia (NR0B1/DAX-1) are at risk of developing hypogonadotropic hypogonadism in adolescence, whereas there is a potential risk of long-term sex steroid insufficiency or hypofertility with partial defects in STAR or CYP11A1/P450scc." (PMID 34258490, 2021). "Mutations in NR0B1 (DAX1) are well established as the cause of X-linked congenital adrenal hypoplasia, primarily characterized by adrenal insufficiency and hypogonadotropic hypogonadism." (PMID 40868191, 2025). "Pathogenic variants in NR0B1 cause X-linked adrenal hypoplasia congenita (AHC), which typically presents with adrenal insufficiency and hypogonadotropic hypogonadism (HH) in boys." (PMID 41300587, 2025). "The duplication of NR0B1 can cause a male-to-female sex reversal phenotype, while variants in NR0B1 lead to CAH associated with hypogonadotropic hypogonadism; this highlights the crucial role of DAX-1 in sex determination and gonadal development." (PMID 34373561, 2021). "Mutations in NR0B1 lead to adrenal hypoplasia congenita (AHC), hypogonadotropic hypogonadism (HH) and azoospermia in men." (PMID 28741070, 2017). "NR0B1 variants can cause infertility in men without the apparent hypogonadotropic hypogonadism." (PMID 37189438, 2023). "We found two patients with one novel variant (c.323–324 CG > GA and c.1231_1234delCTCA) and one infant with an NR0B1 deletion that manifested as PAI, mineralocorticoid deficiency and diminished adrenal glands; however, no hypogonadotropic hypogonadism was noted due to the patient’s young age." (PMID 34193132, 2021).
Adrenal insufficiency (31 papers, 2007 to 2026). Insufficient production of steroid hormones (primarily cortisol) by the adrenal glands. "No other pathogenic variants were found in genes associated with skeletal dysplasias (e.g., FGFR3, COL1A1), adrenal insufficiency (e.g., NR0B1, STAR), or growth retardation (e.g., IGF1R)." (PMID 41218602, 2025). "A previous study reported 117 male children with unexplained adrenal insufficiency, 58% of whom were confirmed to have the NR0B1 variants." (PMID 41300587, 2025). "The severity of clinical characteristics including degree and onset of adrenal insufficiency due to different mutations of NR0B1 has been shown to vary in individuals with adrenal insufficiency and reproductive phenotypes." (PMID 34938333, 2021). "If CHH is associated with severe adrenal insufficiency congenital adrenal hypoplasia caused by NR0B1 (DAX1) is likely." (PMID 32222824, 2021). "NR0B1/DAX-1 mutations should be considered in male infants presenting with isolated hypoaldosteronism as first sign of adrenal insufficiency." (PMID 31164167, 2019). "First, in several children with familial forms of X-linked AHC (NR0B1/DAX-1), MC2R defects or TXNRD2 disruption, we were able to make a diagnosis of adrenal insufficiency early on in the presentation or whilst the child was presymptomatic." (PMID 34258490, 2021). "Indeed, NR0B1 null homozygous male mice have adrenal insufficiency and testicular disorganization, as well as failed spermatogenesis." (PMID 24690677, 2014). "There was no diagnosis of primary adrenal insufficiency, which is consistent with the absence of NR0B1 deletion." (PMID 41583306, 2025). "Translation of this truncated isoform of the NR0B1 (DAX1) protein, possibly exerting some residual activity, might prevent the patient from the classical AHC phenotype and delay the onset of adrenal insufficiency until early adulthood." (PMID 27656210, 2016). "That was why symptoms of adrenal insufficiency were not usually observed after birth (neonatal period), but later (first two months of life or childhood), the adrenal function began to diminish due to shrinkage of progenitor cells, which had been verified in NR0B1‐KO mouse." (PMID 37118935, 2023).